POLR2G (RNA polymerase II subunit G)
Description:
Core component of RNA polymerase II (Pol II), a DNA-dependent RNA polymerase which synthesizes mRNA precursors and many functional non-coding RNAs using the four ribonucleoside triphosphates as substrates. Pol II is the central component of the basal RNA polymerase II transcription machinery. It is composed of mobile elements that move relative to each other. POLR2G/RPB7 is part of a subcomplex with POLR2D/RPB4 that binds to a pocket formed by POLR2A/RPB1, POLR2B/RPB2 and POLR2F/RPABC2 at the base of the clamp element. The POLR2D/RPB4-POLR2G/RPB7 subcomplex seems to lock the clamp via POLR2G/RPB7 in the closed conformation thus preventing double-stranded DNA to enter the active site cleft. The POLR2D/RPB4-POLR2G/RPB7 subcomplex binds single-stranded DNA and RNA.
Synonyms: RPB19; RPB7; hRPB19; hsRPB7
Tractability: Small molecule: a structure with a bound ligand is known. PROTAC: ubiquitination databases record sites on it; its protein half-life has been measured.
Gene: Protein-coding gene on chromosome 11 (62,761,554 to 62,766,715, forward strand). Ensembl gene ENSG00000168002.
Subcellular location: Nucleus
Subcellular location (Human Protein Atlas): Nucleoplasm
Pathways (Reactome):
Disease: Abortive elongation of HIV-1 transcript in the absence of Tat; Dengue Virus-Host Interactions; Formation of HIV elongation complex in the absence of HIV Tat; Formation of HIV-1 elongation complex containing HIV-1 Tat; Formation of the HIV-1 Early Elongation Complex; HIV Transcription Initiation; HIV elongation arrest and recovery; Pausing and recovery of HIV elongation; Pausing and recovery of Tat-mediated HIV elongation; RNA Pol II CTD phosphorylation and interaction with CE during HIV infection; RNA Polymerase II HIV Promoter Escape; Signaling by FGFR2 IIIa TM; Tat-mediated HIV elongation arrest and recovery; Tat-mediated elongation of the HIV-1 transcript; Transcription of the HIV genome; Viral Messenger RNA Synthesis
Gene expression (Transcription): Formation of RNA Pol II elongation complex; Formation of the Early Elongation Complex; MicroRNA (miRNA) biogenesis; PIWI-interacting RNA (piRNA) biogenesis; RNA Pol II CTD phosphorylation and interaction with CE; RNA Polymerase II Pre-transcription Events; RNA Polymerase II Promoter Escape; RNA Polymerase II Transcription Elongation; RNA Polymerase II Transcription Initiation; RNA Polymerase II Transcription Initiation And Promoter Clearance; RNA Polymerase II Transcription Pre-Initiation And Promoter Opening; RNA polymerase II transcribes snRNA genes; Transcriptional regulation by small RNAs
Metabolism of RNA: Processing of Capped Intron-Containing Pre-mRNA; mRNA Capping; mRNA Polyadenylation; mRNA Splicing - Major Pathway; mRNA Splicing - Minor Pathway
DNA Repair: Dual incision in TC-NER; Formation of TC-NER Pre-Incision Complex; Gap-filling DNA repair synthesis and ligation in TC-NER; Transcription-Coupled Nucleotide Excision Repair (TC-NER)
Signal Transduction: Estrogen-dependent gene expression
and 3 more pathways
Gene Ontology:
Molecular function: protein binding; single-stranded DNA binding; single-stranded RNA binding; translation initiation factor binding; nucleic acid binding
Biological process: transcription by RNA polymerase II; transcription elongation by RNA polymerase II; transcription initiation at RNA polymerase II promoter; nuclear-transcribed mRNA catabolic process; positive regulation of nuclear-transcribed mRNA poly(A) tail shortening; positive regulation of translational initiation; DNA-templated transcription; DNA-templated transcription initiation
Cellular component: nucleoplasm; nucleus; RNA polymerase II, core complex; P-body; nuclear DNA-directed RNA polymerase complex
Genetic constraint (gnomAD): Loss-of-function variants: 17 observed, 21.16 expected, observed/expected ratio (o/e) 0.8, 90% interval 0.55 to 1.21. The upper end of that interval is the gene's LOEUF score, 1.21, which puts it in group 5 of 6, group 1 being the genes least tolerant of losing a copy. Missense variants: 107 observed, 191.32 expected, observed/expected ratio (o/e) 0.56, 90% interval 0.48 to 0.66. Synonymous variants: 67 observed, 68.61 expected, observed/expected ratio (o/e) 0.98, 90% interval 0.8 to 1.2.
Homologues: Orthologues: dog POLR2G (100% identical), guinea pig POLR2G (100% identical), mouse Polr2g (100% identical), rabbit POLR2G (100% identical), zebrafish polr2g (99% identical), macaque POLR2G (98% identical), pig POLR2G (98% identical), tropical clawed frog polr2g (97% identical), rat Polr2g (93% identical), Drosophila melanogaster Polr2G (81% identical), Caenorhabditis elegans rpb-7 (77% identical). Paralogues in human: POLR1F (26% identical), POLR3H (17% identical).
Diseases named in the same sentence as POLR2G in open-access papers:
POLR2G is named in the same sentence as 8 diseases in open-access papers, as found by Europe PMC text mining. Sharing a sentence is not in itself a finding about the gene and the disease. The quoted sentences say what the papers report.
cancer (5 papers, 2021 to 2024). A tumor composed of atypical neoplastic, often pleomorphic cells that invade other tissues. "In comparison to the comprehensive investigation of POLD2, POLR2G received comparatively less attention in cancer occurrence and progression." (PMID 39341197, 2024). "By contrast, some other genes encoding the polymerase II subunits were characterized by higher methylation in carcinomas than in BOTS (e.g., promoters and/or first exons of POLR2G and POLR2L, as well as the distal promoter of POLR2C, and the cds of POLR2E, GR file)." (PMID 39456618, 2024).
POLR2G also shares sentences with these, for which no sentence is quoted: tumor (3 papers); asthma (1); breast carcinoma (1); chronic obstructive pulmonary disease (1); gastric carcinoma (1); Gestational Diabetes Mellitus (1); hepatocellular carcinoma (1).